AFG3L1P (AFG3 like matrix AAA peptidase subunit 1, pseudogene)
Synonyms: formerly AFG3; AFG3L1
Gene: Transcribed unitary pseudogene on chromosome 16 (89,972,631 to 90,000,668, forward strand). Ensembl gene ENSG00000223959.
Diseases named in the same sentence as AFG3L1P in open-access papers:
AFG3L1P is named in the same sentence as 3 diseases in open-access papers, as found by Europe PMC text mining. Sharing a sentence is not in itself a finding about the gene and the disease. The quoted sentences say what the papers report.
lung carcinoma (1 paper, 2017). "In network, 4 pseudogenes (RRP7B, RPLP0P2, MSTO2P and AFG3L1P) co-methylated with EZH2, suggesting an involvement in the progression of lung cancer." (PMID 28938616, 2017).
AFG3L1P also shares sentences with these, for which no sentence is quoted: bone marrow failure (1 paper); Fanconi anaemia (1).